ENSG00000285791 (novel transcript)
Gene: Protein-coding gene on chromosome 8 (66,432,486 to 66,518,524, forward strand). Ensembl gene ENSG00000285791.
Genetic constraint (gnomAD): Missense variants: 335 observed, 328.27 expected, observed/expected ratio (o/e) 1.02, 90% interval 0.93 to 1.12. Synonymous variants: 106 observed, 127.72 expected, observed/expected ratio (o/e) 0.83, 90% interval 0.71 to 0.98.